PPP1CB (protein phosphatase 1 catalytic subunit beta)
Description:
Protein phosphatase that associates with over 200 regulatory proteins to form highly specific holoenzymes which dephosphorylate hundreds of biological targets. Protein phosphatase (PP1) is essential for cell division, it participates in the regulation of glycogen metabolism, muscle contractility and protein synthesis. Involved in regulation of ionic conductances and long-term synaptic plasticity. Component of the PTW/PP1 phosphatase complex, which plays a role in the control of chromatin structure and cell cycle progression during the transition from mitosis into interphase. In balance with CSNK1D and CSNK1E, determines the circadian period length, through the regulation of the speed and rhythmicity of PER1 and PER2 phosphorylation. May dephosphorylate CSNK1D and CSNK1E. Dephosphorylates the 'Ser-418' residue of FOXP3 in regulatory T-cells (Treg) from patients with rheumatoid arthritis, thereby inactivating FOXP3 and rendering Treg cells functionally defective. Core component of the SHOC2-MRAS-PP1c (SMP) holophosphatase complex that regulates the MAPK pathway activation. The SMP complex specifically dephosphorylates the inhibitory phosphorylation at 'Ser-259' of RAF1 kinase, 'Ser-365' of BRAF kinase and 'Ser-214' of ARAF kinase, stimulating their kinase activities. The SMP complex enhances the dephosphorylation activity and substrate specificity of PP1c.
Synonyms: PP-1B; PPP1CD; PP1Cbeta; PP1Cdelta; PP1B; PP1beta; PP1c; MP; PPP1beta; HEL-S-80p; NSLH2
Tractability: PROTAC: ubiquitination databases record sites on it; its protein half-life has been measured.
Target class: Protein Phosphatase; Phosphatase; Serine/threonine protein phosphatase; Enzyme
Gene: Protein-coding gene on chromosome 2 (28,751,562 to 28,802,940, forward strand). Ensembl gene ENSG00000213639.
Subcellular location: Cytoplasm; Nucleus; Nucleus, nucleoplasm; Nucleus, nucleolus
Subcellular location (Human Protein Atlas): Nucleoplasm; Cytosol
Pathways (Reactome):
Signal Transduction: Downregulation of TGF-beta receptor signaling; RAF activation; RHO GTPases Activate ROCKs; RHO GTPases activate CIT; RHO GTPases activate PAKs; RHO GTPases activate PKNs
Disease: Gain-of-function MRAS complexes activate RAF signaling; Maturation of hRSV A proteins; SHOC2 M1731 mutant abolishes MRAS complex function
Cell Cycle: Regulation of PLK1 Activity at G2/M Transition
Circadian clock: Phosphorylation and nuclear translocation of the CRY:PER:kinase complex
Metabolism: Triglyceride catabolism
Metabolism of RNA: mRNA Polyadenylation
Gene Ontology:
Molecular function: myosin-light-chain-phosphatase activity; protein binding; protein kinase binding; myosin phosphatase activity; phosphatase activity; protein serine/threonine phosphatase activity; hydrolase activity; phosphoprotein phosphatase activity
Biological process: regulation of cell adhesion; regulation of circadian rhythm; circadian regulation of gene expression; entrainment of circadian clock by photoperiod; MAPK cascade; positive regulation of Ras protein signal transduction; protein dephosphorylation
Cellular component: chromosome, telomeric region; cytosol; extracellular exosome; focal adhesion; nucleoplasm; nucleus; PTW/PP1 phosphatase complex; cytoplasm; nucleolus
Genetic constraint (gnomAD): Loss-of-function variants: 2 observed, 25.44 expected, observed/expected ratio (o/e) 0.0786, 90% interval 0.031 to 0.25. The upper end of that interval is the gene's LOEUF score, 0.25, which puts it in group 1 of 6, group 1 being the genes least tolerant of losing a copy. Missense variants: 66 observed, 285.19 expected, observed/expected ratio (o/e) 0.23, 90% interval 0.19 to 0.28. Synonymous variants: 102 observed, 103.61 expected, observed/expected ratio (o/e) 0.98, 90% interval 0.84 to 1.16.
Gene-disease validity (ClinGen):
ClinGen rates the evidence that PPP1CB causes each of these diseases.
Noonan syndrome-like disorder with loose anagen hair (autosomal dominant): Definitive.
Homologues: Orthologues: dog PPP1CB (100% identical), guinea pig PPP1CB (100% identical), mouse Ppp1cb (100% identical), rat Ppp1cb (100% identical), tropical clawed frog ppp1cb (99% identical), zebrafish ppp1cb (98% identical), macaque PPP1CB (97% identical), chimpanzee PPP1CB (97% identical), pig PPP1CB (97% identical), rabbit PPP1CB (95% identical), Caenorhabditis elegans gsp-1 (90% identical), Drosophila melanogaster flw (90% identical), and 1 more. Paralogues in human: PPP1CA (88% identical), PPP1CC (87% identical), PPP2CB (45% identical), PPP2CA (45% identical), PPP4C (44% identical), PPP6C (41% identical), PPP3CB (39% identical), PPP3CA (38% identical), PPP3CC (38% identical), PPP5C (34% identical), PPEF2 (33% identical), PPEF1 (33% identical).
Diseases named in the same sentence as PPP1CB in open-access papers:
PPP1CB is named in the same sentence as 75 diseases in open-access papers, as found by Europe PMC text mining. Sharing a sentence is not in itself a finding about the gene and the disease. The quoted sentences say what the papers report.
breast carcinoma (8 papers, 2009 to 2023). "Inactivation of PPP1CB caused chronic lymphocytic leukemia, whereas CCNE2 was related to the development of non-small cell lung cancer and breast cancer." (PMID 26308735, 2015). "The gene expression microarray data that we use show a higher expression level of PPP1CB in BRCA1-mutant cancers than in sporadic breast cancers." (PMID 19695104, 2009). "In the same study, RT-PCR expression analysis indicates that sporadic breast cancers have lower expression levels of PPP1CB than do normal tissues." (PMID 19695104, 2009). "In the Oncomine database, when compared with normal breast tissues, PPP1CA, PPP2CA, PPP4C and PPEF1 were significantly elevated in breast cancer tissues, while PPP1CB, PPP2CB, PPP3CA, PPP3CB, PPP3CC and PPP6C were significantly decreased in breast cancer tissues." (PMID 34964699, 2022). "In our study there are 12 nonBRCA1-mutant samples which exhibit the relation RNF14 <TMEM57 <PPP1CB, of which 7 are "basal-like" tumors, a subtype of breast cancer associated with lack of expression of the estrogen receptor and poor prognosis." (PMID 19695104, 2009). "Except for PPP1CB, PPP1CC, PPP5C and PPEF1, the mRNA expression levels of the PPPCs family in breast cancer tissues were significantly different from those in paracancerous tissues." (PMID 34964699, 2022).
hepatocellular carcinoma (5 papers, 2017 to 2026). A malignant tumor that arises from hepatocytes. "A genetic variant of PPP1CB (rs13025377) was found to influence the risk of hepatitis B virus-related hepatocellular carcinoma (HCC) in Han Chinese populations." (PMID 41511815, 2026). "It contains PPP1CB, which is an interesting hit, although not found by other programs, since it has been found in the first 40 up-regulated genes in HCV-related Hepatocellular carcinoma (HCC) samples analyzed by De Giorgi and colleagues." (PMID 28949986, 2017).
glioblastoma (4 papers, 2020 to 2024). The most malignant astrocytic tumor (WHO grade IV). "PPP1CB is highly expressed in a variety of human cancers, including pancreatic adenocarcinoma (PAAD), glioblastoma multiforme (GBM), thymoma (THYM), and brain lower grade glioma (LGG) (P < 0.05), compared to normal tissue." (PMID 34125004, 2021).
Noonan-like syndrome (4 papers, 2018 to 2024). "Of the three catalytic subunit encoding genes, only PPP1CB has been defined as the cause of a congenital disease, i.e. Noonan-like syndrome with loose anagen hair-2." (PMID 36313552, 2022). "The involvement of PPP1CB in Noonan syndrome-like disorders was first found in 2016, when four patients presented with typical symptoms of this disorder, including distinctive hair anomalies, developmental differences, and structural brain abnormalities (OMIM#617506)." (PMID 36313552, 2022).
pancreatic cancer (4 papers, 2010 to 2023). "In order to investigate the expression of PPP1CB in pancreatic cancer and its clinical prognostic value, we first performed a bioinformatics analysis." (PMID 34125004, 2021). "Among all the PPPcs, PPP1CB, PPP1CC, PPP2CA, PPP2CB, PPP3CB, and PPP5C had tight associations with at least one of the pancreatic cancer related genes in that list." (PMID 33270085, 2021). "Results of the present study suggest that PPP1CA, PPP1CB, PPP2CA, PPP2CB, and PPP3CA have deleterious effects but PPP3CB, PPP5C, and PPP6C have beneficial effects on pancreatic cancer." (PMID 33270085, 2021). "A trend was seen in PPP1CA, PPP1CB, and PPEF1: they were also overexpressed in pancreatic cancer, with fold changes between 1.5 and 2.0." (PMID 33270085, 2021). "In recent years, it has been reported that PPP1CA, PPP1CB, PPP2CA, PPP2CB, and PPP3CA accelerate the progression of pancreatic cancer, while PPP3CB, PPP5C, and PPP6C hinder PAAD progression." (PMID 34125004, 2021). "Among all the PPPcs, the transcription levels of PPP1CA, PPP1CB, PPP3CA, PPP3CB, and PPP4C were higher in pancreatic cancer than in the normal pancreas." (PMID 33270085, 2021). "Data from THPA and patients with pancreatic cancer enrolled in our hospital also confirmed the prognostic value of PPP1CA, PPP1CB, PPP2CA, PPP2CB, PPP3CA, PPP3CB, and PPP6C at the protein level." (PMID 33270085, 2021). "In addition, only PPP3CB and PPP6C showed favorable prognostic values with regard to protein level, whereas PPP1CA, PPP1CB, PPP1CC, PPP2CA, PPP2CB, and PPP3CA showed unfavorable prognostic values in pancreatic cancer (P<0.05)." (PMID 33270085, 2021).
RASopathy (4 papers, 2019 to 2025). Developmental syndromes caused by germline mutations (or in rare cases by somatic mosaicism) in genes that alter the Ras subfamily and mitogen-activated protein kinases that control signal transduction. "This 24% is higher than the one observed for other RASopathy proteins, including but not limited to PPP1CB, and similar to NF1." (PMID 34229750, 2021).
melanoma (3 papers, 2021 to 2025). A malignant, usually aggressive tumor composed of atypical, neoplastic melanocytes. "PPP1CB is also associated with metastasis in gastric cancer and melanoma, and is a latent anti-metastatic target for the treatment of early stage melanoma." (PMID 34125004, 2021). "Interestingly, PPP1CB-TAI was also identified in single-cell data on melanoma and within TCGA bulk RNAseq data it was also more frequent in tumors across cancer types compared to matched normal tissue." (PMID 41273175, 2025). "For two ASEs, we detected at least one atypical isoform in both BC and melanoma: one occurring in UQCRB and another in the protein phosphatase 1 catalytic subunit beta (PPP1CB) that was detected in up to 30 patients." (PMID 41273175, 2025). "PPP1CB-TAI isoform proportions were significantly correlated with objective response rates in mUC and one melanoma cohort (likelihood ratio test, P < 0.05), while in NSCLC the association was almost significant (P < 0.1)." (PMID 41273175, 2025). "Because of its high frequency both in BC and melanoma, we further investigated the atypical ASE affecting PPP1CB." (PMID 41273175, 2025). "In addition, studies have reported that PPP1CB has a positive relationship with the proliferation, migration and invasion of prostate cancer, gastric cancer, and melanoma, however studies have not evaluated the specific role of PPP1CB." (PMID 34125004, 2021).
Obesity (3 papers, 2017 to 2024). Accumulation of substantial excess body fat. "Our MR results found a significant causal relationship between PPP1CB and obesity, suggesting that inhibition of PPP1CB may reduce the risk of obesity." (PMID 39351493, 2024). "The expressions of CSNK1E (OR: 0.922, 95% CI: 0.853–0.997, p = 0.043) and PPP1CB (OR: 0.958; 95% CI: 0.922–0.995; p = 0.027) may be associated with a lower risk of obesity, while BHLHE40 (OR: 1.093, 95% CI: 1.010–1.183, p = 0.0028) may be associated with a higher risk of obesity." (PMID 39351493, 2024). "BHLHE40 was found to promote obesity through various pathways, while PPP1CB and CSNK1E counteracted lipid metabolism disorders, and modulated cytokines, immune receptors, T cells, and monocytes." (PMID 39351493, 2024). "Our study identified three key circadian genes (BHLHE40, PPP1CB, and CSNK1E) associated with obesity." (PMID 39351493, 2024). "Considering all these facts, the identification of PPP1CB inhibitors is a good strategy to find potent therapeutic medicines for obesity." (PMID 35055051, 2022). "As part of our ongoing efforts to discover new anti-obesity natural products, we verified the inhibitory effects of 1033 natural products on PPP1CB using the 6,8-difluoro-4-methylumbelliferyl phosphate (DiFMUP) inhibition assay." (PMID 35055051, 2022). "Our research findings suggest that the circadian genes (BHLHE40, CSNK1E, and PPP1CB) could serve as novel biomarkers for understanding the pathogenesis of obesity." (PMID 39351493, 2024). "Thus, chebulinic acid is a potent and novel compound for obesity treatment through PPP1CB inhibition." (PMID 35055051, 2022). "Current results suggest that PPP1CB may be the target of these compounds for the anti-obesity effect." (PMID 35055051, 2022). "In conclusion, the key circadian genes (BHLHE40, CSNK1E, and PPP1CB) may serve as novel biomarkers for understanding obesity pathogenesis and have significant correlations with infiltrating immune cells, thus providing potential new targets for obese prevention and treatment." (PMID 39351493, 2024). "However, there have been no reports on the association between PPP1CB expression levels and obesity in humans." (PMID 39351493, 2024). "PPP1CB might inhibit the progression of obesity by managing lipid metabolism directly." (PMID 39351493, 2024). "Therefore, PPP1CB is considered as a potential therapeutic target for obesity." (PMID 35055051, 2022). "Abnormal expressions of PPP1CB and CSNK1E in obesity directly affect the core clock genes (PER1, PER2), and the accumulation of PERs and CRYs in the nucleus inhibits the transcription of CLOCK and BMAL1, disrupting energy homeostasis and leading to obesity." (PMID 39351493, 2024). "PPP1CB can dephosphorylate CSNK1E, suggesting that these two genes may contribute to the immune landscape in obesity collectively." (PMID 39351493, 2024). "However, no studies have focused on the role of PPP1CB in immune inflammation and pathogenesis in obesity." (PMID 39351493, 2024).
congenital heart disease (2 papers, 2019 to 2022). A heart disease that is present at birth. "Furthermore (other) mutations in PPP1CB have been implied as causative of intellectual disability and congenital heart disease." (PMID 36313552, 2022). "Missense variants in PPP1Cb gene were also implicated in congenital heart disease." (PMID 30721967, 2019).
glioma (2 papers, 2022 to 2024). A benign or malignant brain and spinal cord tumor that arises from glial cells (astrocytes, oligodendrocytes, ependymal cells). "However, the functional role and underlying mechanism of SMOC1, HIPK2, UBA52, S100A6, PPP1CB, CALD1, and TMSB4X in the occurrence and development of diffuse high-grade gliomas was still unknown." (PMID 39530009, 2024).
lung adenocarcinoma (2 papers, 2021 to 2024). A carcinoma that arises from the lung and is characterized by the presence of malignant glandular epithelial cells. "Together, this study revealed the critical non‐epigenetic role of NSD3 in the regulation of STAT3‐dependent glycolysis, providing a piece of compelling evidence for targeting the NSD3/PPP1CB/p‐STAT3 in lung adenocarcinoma." (PMID 39119928, 2024). "NSD3 formed protein trimer with PPP1CB and p‐STAT3, thus stimulating p‐STAT3 dephosphorylation by PPP1CB to suppress the transcription of HK2, which ultimately inhibited the Warburg effect in lung adenocarcinoma." (PMID 39119928, 2024). "PPP1CB was not differentially expressed between normal and cancer tissue in other cancers, such as adrenocortical carcinoma (ACC), lung adenocarcinoma (LUAD), or prostate adenocarcinoma (PRAD)." (PMID 34125004, 2021).
osteoporosis (2 papers, 2020 to 2024). A condition of reduced bone mass, with decreased cortical thickness and a decrease in the number and size of the trabeculae of cancellous bone (but normal chemical composition), resulting in increased fracture incidence. "In sum, our present study highlights 36 convincing genes associated with BMD risk and further provides strong evidence to support that PPP1CB represents a genuine BMD-associated risk gene with eSNPs conferring susceptibility to osteoporosis." (PMID 32266926, 2020). "Furthermore, more related molecular studies are warranted to reveal the biological mechanism of PPP1CB gene implicated in osteoporosis." (PMID 32266926, 2020). "Together, we provide a convergent line of evidence to support that the PPP1CB gene involves in the etiology of osteoporosis." (PMID 32266926, 2020). "Our study systematically identified seven candidate hub genes (PDP1, ALS2CL, VLDLR, PLEKHA6, PPP1CB, MOSPD2, and METTL9) through a combination of various bioinformatics analyses and machine learning algorithms, and provided a nomogram for diagnosing sarcopenia associated with osteoporosis." (PMID 38831425, 2024). "A notable finding is the identification of 7 key candidate genes (PDP1, ALS2CL, VLDLR, PLEKHA6, PPP1CB, MOSPD2, and METTL9), and the development of a nomogram for diagnosing osteoporosis in sarcopenia patients." (PMID 38831425, 2024). "We identified 7 candidate hub genes (PDP1, ALS2CL, VLDLR, PLEKHA6, PPP1CB, MOSPD2, METTL9) and constructed column line plots for osteoporosis combined with sarcopenia." (PMID 38831425, 2024).
ovarian carcinoma (2 papers, 2009 to 2023). A malignant neoplasm originating from the surface ovarian epithelium. "Moreover, the literature also suggests that PPP1CB is a discriminator gene between BRCA1-mutant and BRCA2-mutant tumors for both breast and ovarian cancers." (PMID 19695104, 2009).
pancreatic adenocarcinoma (2 papers, 2021). "In this work, we found that the mRNA levels of PPP1CA and PPP1CB in pancreatic adenocarcinoma were higher than those in normal tissues." (PMID 33270085, 2021).
atherosclerosis (1 paper, 2025). A disease characterized by the build-up of fatty material and calcium deposition in the arterial wall resulting in partial or complete occlusion of the arterial lumen. "We identified 12 lactylation-related genes that are more reliably associated with atherosclerosis: five upregulated genes (LSP1, IKZF1, MNDA, RCC2, and WAS) and seven downregulated genes (CSRP2, PPP1CB, CSRP1, HEXIM1, CALD1, PDLIM1, and RANBP2)." (PMID 40248193, 2025).
bladder cancer (1 paper, 2022). "However, this study also found that the high expression of PPP1CB is relevant to the poor prognosis of BC, which revealed that the genes related to fat metabolism are another focus of bladder cancer treatment." (PMID 36741702, 2022). "Weighted gene co-expression network analysis (WGCNA), protein–protein interaction (PPI) network mutual analysis, and the Kaplan–Meier survival prognosis analysis were used to identify six key genes associated with the prognosis of bladder cancer: VEGFA, ANXA1, HSP90B1, PSMA7, PRDX6, and PPP1CB." (PMID 36741702, 2022). "The Kaplan–Meier survival prognosis analysis was performed on the top 100 genes, and 6 genes related to the survival prognosis of bladder cancer were finally screened out: VEGFA, ANXA1, HSP90B1, PSMA7, PRDX6, and PPP1CB." (PMID 36741702, 2022). "According to BC values and the Kaplan–Meier survival curve, six genes related to the occurrence and development of bladder cancer were screened out: VEGFA, ANXA1, HSP90B1, PSMA7, PRDX6, and PPP1CB." (PMID 36741702, 2022).
cardiac hypertrophy (1 paper, 2019). "Additionally, Gde1, which is involved in skeletal muscle development, Pdlim5, a promoter of cardiac hypertrophy, and Ppp1cb, a regulator of cell division, glycogen metabolism, and muscle contractility, were overexpressed." (PMID 31480808, 2019).